KRAS (KRas proto-oncogene, GTPase)
Diseases named in the same sentence as KRAS in open-access papers (continued):
Sharing a sentence is not in itself a finding about the gene and the disease.
lung cancer (continued). "In lung cancer, transcriptional induction of ERBB3 causes intrinsic resistance to MEK inhibition in KRAS-mutant cancers, and acquired resistance to EGFR inhibitors was found to result from amplification of MET." (PMID 28145866, 2017). "Copy number gain of oncogenes including EGFR, KRAS and c-MYC has been reported in lung carcinoma, where it was associated with advanced stage and poor clinical outcome." (PMID 28501852, 2017). "In order to validate Aurora kinases as therapeutic targets for KRAS-induced lung cancer, it is important to show that inhibiting these kinases preferentially targets lung cancer cells expressing oncogenic KRAS." (PMID 26842935, 2016). "Lung cancer is a disease that presents high incidence and mortality rates, and it is primarily associated with genetic mutations that affect the EGFR, KRAS, and EML4-ALK fusion proteins." (PMID 26956044, 2016). "TBK1 was shown to be co-lethal in KRAS mutant lung cancer and it has been investigated as a potential target in triple-negative breast cancer." (PMID 27613601, 2016). "Recently, three discrete subtypes of human KRAS-mutant lung adenocarcinomas were discovered in a breakthrough of our understanding of the variability within this type of lung cancer." (PMID 27301828, 2016). "Mice with KRAS mutant lung cancer treated with the DOPC-mediated siRNA showed decreased downstream signaling, inhibited proliferation, and a decrease in metastatic burden in vivo." (PMID 27096871, 2016). "Collectively, these results suggest that MAPK signaling contributes to ectopic PD-L1 expression in KRAS-mutant lung cancer cell lines." (PMID 27846317, 2016). "In order to validate Aurora kinases as potential therapeutic targets for KRAS-induced lung cancer, it is important to demonstrate that Aurora kinase targeting reduces KRAS-driven tumor growth in vivo." (PMID 26842935, 2016). "Nonetheless, our findings demonstrate that these kinases also support the malignant phenotype of KRAS-transformed lung cancer cells." (PMID 26842935, 2016). "KRAS-positive lung cancer patients are among the most refractory to available treatments, but efforts to develop new therapies for these patients, including anti-MEK drugs, are particularly intensive." (PMID 26968843, 2016). "In this work we demonstrated that AURKA and AURKB are potential new promising targets for KRAS-induced lung cancer therapy." (PMID 26842935, 2016). "It allowed us to test how multiple KRAS mutant lung cancer cell lines differentially respond to MEK inhibition and reveal heterogeneous ATP-binding proteome responses from each individual cell line." (PMID 28154798, 2016). "Here, we analyzed the mutational frequency of EGFR and KRAS gene, as well as EML4-ALK rearrangement, and summarized the clinicopathological characters of Chinese lung cancer patients." (PMID 26739511, 2016). "In KRAS-mutant Calu-1 lung cancer cells shRNA-mediated silencing of KRAS reduces sensitivity to erastin." (PMID 27048822, 2016). "Human lung cancers potentially demonstrate synergistic mutations/deletions of more than one cancer-related genes, such as LKB1 deletion with KRAS mutation, in a subset of poorly differentiated adenocarcinomas." (PMID 26974543, 2016). "Several microRNAs are implicated in inflammation-associated carcinogenesis, and genetic ablation of NOS2 in a genetically engineered mouse model of KRAS-induced lung cancer reduced the expression of oncomir-21." (PMID 27367029, 2016). "Here, we profiled ATP-binding proteome responses to two clinical MEK inhibitors, AZD6244 and MEK162, in the context of KRAS mutant lung cancer." (PMID 28154798, 2016). "In this study, we characterized the clinicopathologic features and genetic changes associated with EGFR, KRAS, and ALK in lung cancer." (PMID 26992209, 2016). "Although there haven't been any therapeutic approaches for KRAS-positive lung cancer approved, mutant KRAS is still a promising potential therapeutic target in the high-risk population." (PMID 27563816, 2016).
lung cancer (continued). "MAPK signaling has been known to be essential for KRAS-induced lung tumorigenesis, and pharmacological inhibition of this pathway (e.g., MEK inhibitor) has been attempted to treat KRAS-driven lung cancers." (PMID 28154798, 2016). "In contrast, HIF1α deletion in a KRAS-driven mouse model of lung cancer had negligible effect on tumor burden and progression, whereas a deletion in its isoform, HIF2α increased tumor growth and progression." (PMID 27708247, 2016). "For this purpose, we stably integrated GFP-tagged histone H2B into an isogenic pair of lung cancer cell lines that only differ in their KRAS genotype (NCI-H1975 KRAS+/+ and KRASG12D/+), and monitored cell division by time-lapse microscopy." (PMID 27412232, 2016). "miR-206 was proved to act as a tumor suppressor miRNA in lung cancer through targeting the KRAS, FMNL2 and SOX9." (PMID 27906963, 2016). "EZH2 inhibition enhances the sensitivity to MEK-ERK or PI3K/AKT targeted therapies in specific KRAS-mutant lung cancer cells and tumors." (PMID 27494834, 2016). "Hk2 has been identified as an attractive target for KRAS-driven lung cancers as whole-body deletion of Hk2 in the mouse selectively targets tumor cells." (PMID 27096871, 2016). "Activation of YAP is crucial in KRAS-driven colon and lung cancer because KRAS and YAP converge to regulate epithelial-mesenchymal transition." (PMID 27589805, 2016). "To further investigate the S100A10 levels in clinically relevant cancer cell lines, we depleted KRAS from A549 (lung cancer) and MiaPaca2 (pancreatic cancer) cells and analysed S100A10 expression by western blotting." (PMID 27351226, 2016). "Here, we mapped global ATP-binding proteomes perturbed by two clinical MEK inhibitors, AZD6244 and MEK162, in KRAS mutant lung cancer cells as a model system harnessing a desthiobiotin-ATP probe coupled with LC-MS/MS." (PMID 28154798, 2016). "This is particularly important in lung cancer: repeat biopsy is rarely performed, even though various studies have shown discrepancies in EGFR, ALK and KRAS mutational status." (PMID 26968843, 2016). "Non-small-cell lung carcinoma (NSCLC) is the most prevalent type of lung cancer, and KRAS is the driving oncogene in about 20 to 30% of these cases." (PMID 27911940, 2016). "Global phosphoproteome (phospho-Ser/Thr/Tyr) profiling showed that ablation of TBK1 expression in KRAS mutant lung cancers leads to compensatory activation of a panel of receptor tyrosine kinases including EGFR and MET." (PMID 28154798, 2016). "While the role of NOS enzymes in cancer is complex, with regards to KRAS mutation-positive NSCLC, the murine lung cancer cell line LLC was reported to grow more poorly when implanted into eNOS−/− mice." (PMID 27285753, 2016). "By these approaches, we have shown that these kinases are important for growth and viability of KRAS-positive lung cancer cells." (PMID 26842935, 2016). "In spite of the considerable published data on the prevalence of EGFR mutations in lung cancer throughout the world, only a few papers present data on EGFR, KRAS and ALK mutations in countries from Central Europe." (PMID 27655296, 2016). "The most frequent mutation of KRAS is localized in codon 12 (G12C), which affects approximately one third of the experimentally used NSCLC-lines and 30% of patients with lung cancer." (PMID 27780929, 2016). "Unfortunately, data concerning evaluation of the KRAS gene status simultaneously in corresponding metastatic lesions and primary lung carcinomas are limited." (PMID 25902737, 2016). "The most promising approach for KRAS mutant lung cancer seems to be the inhibition of MEK in combination with conventional chemotherapy." (PMID 26018876, 2015). "This combination was further profiled in a KRAS-wild type lung cancer cell line, and a pair of KRAS-mutant and wild type colon cancer cell lines." (PMID 26018524, 2015).
lung cancer (continued). "KRAS mutant lung cancer comprises 25-30% of lung adenocarcinomas and unfortunately no effective treatment is currently available for this sub-type of non-small cell lung cancer (NSCLC)." (PMID 25956913, 2015). "We also evaluated IC50 values for afatinib in gefitinib-resistant human lung cancer H1975 cells carrying de novo T790M mutation, and in H460 cells which express wild-type of EGFR but carrying KRAS mutation which leads to gefitinib resistance." (PMID 25714021, 2015). "A similar explanation also underlies the mutual exclusivity for KRAS and EGFR mutations seen in lung cancer." (PMID 26427375, 2015). "The CLTPM1L gene, also known as cisplatin resistance-related protein 9 (CRR9p), encodes a protein that is overexpressed in lung and pancreatic cancer, promotes growth and survival, and is required for KRAS driven lung cancer." (PMID 26372813, 2015). "BRAF mutations, although detected at lower frequencies in lung cancer, have emerged as an alternative important mechanism of MAPK signaling activation downstream of KRAS." (PMID 26208325, 2015). "We have demonstrated that STAT3 has a tumour-suppressor function in murine Kras mutant lung cancer as well as in human KRAS mutant xenografts." (PMID 25734337, 2015). "Other therapeutic approaches for KRAS mutant lung cancer are the inhibition of other downstream signaling pathways as PI3K and focal adhesion kinase (FAK)." (PMID 26018876, 2015). "It is plausible that LAPTM4B-NRF2 signaling is modulated differentially in different cell lines with distinct mutational, genetic and epigenetic profiles; being more activated in KRAS mutant compared to wild type lung cancer cells." (PMID 26343532, 2015). "We selected KRAS for this investigation because it bears indisputable hotspot somatic SNV for lung cancer in codons 12 and 13, which have been previously well identified." (PMID 26076459, 2015). "Our panel included 22 genes, although the approved predictive biomarkers in colon and lung cancer are quite few (KRAS, NRAS, EGFR, ALK)." (PMID 25637035, 2015). "Through synthetic lethality screening using a chemical library for isogenic cell lines with and without oncogenic KRAS, we previously reported a small molecule, designated oncrasin-1, that induces apoptosis in several KRAS-mutant lung cancer cell lines." (PMID 26134262, 2015). "Clinically relevant driver mutations, e.g., in EGFR, KRAS, and ELM4-ALK fusion, were present in 40% of the lung cancer patients." (PMID 26496203, 2015). "To search for targeted synergies, we combined the growth factor signaling inhibitor TAK-165 with an inhibitor of proliferation (trametinib) or a cell cycle inhibitor (MLN-8054) in proliferation assays with the KRAS-mutant A427 lung cancer cell line." (PMID 26018524, 2015). "The most promising agents in development for KRAS mutant lung cancer have been MEK inhibitors combined with chemotherapy." (PMID 25505733, 2014). "Lung cancer therapy has changed enormously over the last years thanks to the discovery of specific mutations (EGFR, KRAS, ALK, ROS1), and thus the introduction of targeted therapies." (PMID 25593996, 2014). "It is detected in particularly high rates in lung cancer, occurring in 40% of KRAS mutant lung tumours." (PMID 25361007, 2014). "Acquired resistance to KRAS suppression in a KRAS-driven murine lung cancer model involves increased YAP1 signaling." (PMID 26137517, 2014).
lung cancer (continued). "Here, genetic and pharmacological approaches were utilized to inactivate IKK in human primary lung epithelial cells transformed by KRAS, as well as KRAS mutant lung cancer cell lines." (PMID 24955217, 2014). "Here, we demonstrated that CmpdA inhibits NF-κB activity in other KRAS positive lung cancer cell lines as well." (PMID 24955217, 2014). "Oncogenic KRAS binds and activates CRAF more efficiently and mediates KRAS signaling to ERK kinase in lung cancer cells, thus fulfilling an important role as an anti-apoptotic protein independent of BRAF." (PMID 25013473, 2014). "Here we show that pharmacological inhibition of IKKβ in primary human lung epithelial cells transformed by KRAS, as well as KRAS mutant lung cancer cell lines, inhibits NF-κB activity and reduces cell growth." (PMID 24955217, 2014). "Across the panel of NSCLC lines, bosutinib reduced cell viability at micromolar IC50 of between 1–5 μM via apoptosis in all tested KRAS mutant and KRAS wild type (WT) lung cancer cell lines." (PMID 24461128, 2014). "To further investigate Sox9 overexpression in lung ADC, we queried data with annotated mutational information and analyzed Sox9 expression within lung cancer genetic subgroups, including EGFR and KRAS mutations." (PMID 25004243, 2014). "It has been shown that the let-7 family inhibits KRAS resulting in slower proliferation and tumor growth of lung cancer cells." (PMID 24368337, 2014). "The potential benefit of the proteome modulated by oncogenic KRAS to lung cancer research has been demonstrated." (PMID 24503901, 2014). "However, the proportions of tested patients with colon and lung cancers with KRAS mutation were slightly higher than published data, perhaps in part reflecting the referral pattern in our Phase I Program, which may be affected by the availability of MEK inhibitor trials." (PMID 25313136, 2014). "In order to test IKKβ inhibition therapy as an approach to treat KRAS-induced lung cancer we used CmpdA, a highly specific IKKβ inhibitor." (PMID 24955217, 2014). "With the development of molecular subtype in lung cancer, NSCLC patients with EGFR-WT had been identified to carry several new “driver mutations”, including KRAS, HER2, and BRAF mutations, as well as ALK, ROS1, and RET gene fusion." (PMID 25277203, 2014). "In lung cancer, EGFR response is tightly correlated with activating EGFR mutations, while resistance in colon cancer is mediated by downstream KRAS mutations." (PMID 25428177, 2014). "The KRAS oncogene was one of the earliest discoveries of genetic alterations in colorectal and lung cancers." (PMID 24884535, 2014). "Since oncogenic KRAS is frequently found in many cancers, including colon, pancreatic, and lung cancer, and different cancer types and stages exhibit distinctive miRNA profiles, the regulation of KRAS by miRNAs has drawn attention in the field." (PMID 25433809, 2014). "Evidence supporting these mechanistic scenarios includes, the identification of a SNP associated with increased risk of lung cancer and ovarian cancer, that alters a let-7 miRNA binding site in the 3'UTR of the KRAS transcript." (PMID 25245095, 2014). "The response rate with single agent trametinib is 12%, with similar activity to docetaxel in pre-treated KRAS mutant lung cancer patients." (PMID 25505733, 2014). "In this article, we review the four commonly known oncogenic driver mutations in lung cancer – EGFR mutations at exons 18 – 21, KRAS gene mutation at codons 12 and 13, EML4-ALK fusion genes and deregulation of MET signaling." (PMID 27234388, 2013).
lung cancer (continued). "The PIK3CA pathway consist of the KRAS and EGFR genes which are important targets for many cancers, mutations of PIK3CA have been also identified in lung cancer." (PMID 24369052, 2013). "Other well defined markers of lung cancer are the Kirsten rat sarcoma viral oncogene homolog (KRAS) and Epidermal growth factor receptor (EGFR)." (PMID 23384026, 2013). "We performed a comprehensive analysis of EGFR/KRAS mutation and ALK rearrangement in a total of 360 surgically resected lung cancers." (PMID 23936355, 2013). "Tumors arising in the RASLO mice treated with AdCre comprised multiple papillary adenomas and invasive papillary adenocarcinomas, which is consistent with KRAS driven lung cancer models described previously." (PMID 23536778, 2013). "The EGFR/KRAS mutations and the EML4-ALK translocation are called driver mutations because they are responsible for both the initiation and maintenance of lung cancer." (PMID 23341890, 2013). "After confirmation of the quality of the probes, the in situ genotyping method was applied to ten fresh frozen human colon and lung cancer tissues with known KRAS status." (PMID 24280411, 2013). "These tumors range from papillary adenomas to invasive papillary adenocarcinomas, which is consistent with KRAS-driven lung cancer models described previously." (PMID 23536778, 2013). "Earlier studies have noted similar KRAS mutations in both the primary tumor and metastases in more than 90% of patients with CRC or lung cancer." (PMID 24304820, 2013). "EGFR, KRAS, and BRAF mutations and EGFR antibody treatment (colorectal carcinoma) and EGFR inhibitor treatment (lung carcinoma) serve as good examples." (PMID 24764475, 2013). "One strategy for targeting KRAS-driven lung cancer is to determine crucial downstream signaling cascades that, when inhibited, cause cell death in the presence of the driver mutation, but not the presence of a wild-type allele." (PMID 22928112, 2012). "Let-7, the first miRNA identified to be aberrantly expressed in lung cancer, targets KRAS and HMGA2, resulting in suppression of proliferation, with reduced let-7 expression correlating with poor clinical outcome." (PMID 22852089, 2012). "In lung cancer patients, EGFR mutations are generally exclusive with KRAS and BRAF mutations, and tumors with either KRAS (15–25%) or BRAF (2-3%) mutations are relatively insensitive to EGFR TKIs." (PMID 22970367, 2012). "NLE has shown tumor-inhibitory effects of let-7 NLE formulations in a mouse model of lung cancer (a transgenic mouse with a constitutively activated KRAS) with an already established lung tumor." (PMID 22348396, 2012). "The consequences of knocking down TWIST1 using shRNA technology was tested in human KRAS mutant H460 lung cancer cells." (PMID 22654667, 2012). "In mouse models of oncogenic KRAS-induced lung cancer, PX-866 was able to halt PI3K-induced bronchioalveolar stem cell expansion." (PMID 24281308, 2012). "The generality of our results using different cell types and across species suggest TWIST1 is a potential therapeutic target in KRAS mutant lung cancers." (PMID 22654667, 2012). "Pyrosequencing of the KRAS gene in codon 12 and 13 revealed that both the pancreatic carcinoma and the lung carcinoma harbored an identical codon 12 c." (PMID 23119210, 2012).